CIB2 (calcium and integrin binding family member 2)
Description:
Calcium- and integrin-binding protein that plays a role in intracellular calcium homeostasis (By similarity). Acts as an auxiliary subunit of the sensory mechanoelectrical transduction (MET) channel in hair cells (By similarity). Essential for mechanoelectrical transduction (MET) currents in auditory hair cells and thereby required for hearing (By similarity). Regulates the function of hair cell mechanotransduction by controlling the distribution of transmembrane channel-like proteins TMC1 and TMC2, and by regulating the function of the MET channels in hair cells (By similarity). Required for the maintenance of auditory hair cell stereocilia bundle morphology and function and for hair-cell survival in the cochlea (By similarity). Critical for proper photoreceptor cell maintenance and function (By similarity). Plays a role in intracellular calcium homeostasis by decreasing ATP-induced calcium release.
Synonyms: KIP2; DFNB48; USH1J
Tractability: Antibody: UniProt places it where antibodies can reach, with medium confidence; its Gene Ontology location is reachable by antibodies, with medium confidence.
Gene: Protein-coding gene on chromosome 15 (78,104,606 to 78,131,535, reverse strand). Ensembl gene ENSG00000136425.
Subcellular location: Cytoplasm; Cell projection, stereocilium; Photoreceptor inner segment; Cell projection, cilium, photoreceptor outer segment; Cell membrane, sarcolemma
Subcellular location (Human Protein Atlas): Nucleoplasm; Centrosome; Cytosol; Primary cilium transition zone
Pathways (Reactome):
Sensory Perception: Sensory processing of sound by inner hair cells of the cochlea; Sensory processing of sound by outer hair cells of the cochlea
Gene Ontology:
Molecular function: calcium ion binding; magnesium ion binding; protein binding; protein homodimerization activity; integrin binding; protein-containing complex binding
Biological process: cellular response to ATP; positive regulation of cytosolic calcium ion concentration; calcium ion homeostasis; photoreceptor cell maintenance
Cellular component: blood microparticle; cuticular plate; stereocilium; cell periphery; cytoplasm; photoreceptor inner segment; photoreceptor outer segment; muscle tendon junction; neuromuscular junction; sarcolemma
Genetic constraint (gnomAD): Loss-of-function variants: 19 observed, 21.89 expected, observed/expected ratio (o/e) 0.87, 90% interval 0.61 to 1.27. The upper end of that interval is the gene's LOEUF score, 1.27, which puts it in group 5 of 6, group 1 being the genes least tolerant of losing a copy. Missense variants: 220 observed, 247.73 expected, observed/expected ratio (o/e) 0.89, 90% interval 0.8 to 0.99. Synonymous variants: 94 observed, 95.34 expected, observed/expected ratio (o/e) 0.99, 90% interval 0.83 to 1.17.
Gene-disease validity (ClinGen):
ClinGen rates the evidence that CIB2 causes each of these diseases.
nonsyndromic genetic hearing loss (autosomal recessive): Definitive. A disease characterized by hearing loss that is not part of a larger syndrome.
Usher syndrome type 1 (autosomal recessive): Refuted.
Homologues: Orthologues: chimpanzee CIB2 (100% identical), macaque CIB2 (100% identical), rat Cib2 (98% identical), guinea pig CIB2 (98% identical), pig CIB2 (98% identical), mouse Cib2 (97% identical), rabbit CIB2 (91% identical), dog CIB2 (83% identical), tropical clawed frog cib2 (80% identical), zebrafish cib2 (76% identical), Drosophila melanogaster Cib2 (59% identical), Caenorhabditis elegans calm-1 (51% identical), and 5 more. Paralogues in human: CIB3 (61% identical), CIB4 (37% identical), CIB1 (36% identical), CHP1 (26% identical), CHP2 (26% identical), PPP3R1 (25% identical), PPP3R2 (25% identical), TESC (24% identical).
Diseases named in the same sentence as CIB2 in open-access papers:
CIB2 is named in the same sentence as 30 diseases in open-access papers, as found by Europe PMC text mining. Sharing a sentence is not in itself a finding about the gene and the disease. The quoted sentences say what the papers report.
Usher syndrome (20 papers, 2014 to 2025). A syndromic diseae characterized by the association of sensorineural deafness (usually congenital) with retinitis pigmentosa and progressive vision loss. "Following the identification of CIB2 as a causative gene in Usher syndrome type 1 J and non-syndromic deafness, a number of investigations have established a prominent role of CIB2 in hearing physiology and disease." (PMID 35408910, 2022). "Recent findings demonstrate the involvement of CIB2 in hearing physiology and a single, conservative point mutation (p.E64D) has been related to Usher Syndrome type 1J (USH1J) and non-syndromic hearing loss." (PMID 30174586, 2018). "To date, mutations detected in CIB2 are causative for nonsyndromic hearing loss (DFNB48) or Usher syndrome type 1 J." (PMID 27771768, 2017). "Different disorders other than HI or Usher syndrome have also been linked to the 15q24 locus, containing the CIB2 gene." (PMID 27771768, 2017). "Mutations in ADGRV1 and CIB2 have been linked to three separate subtypes of Usher syndrome." (PMID 39060957, 2024). "Notably, Müller glial cells also expressed the other USH1-associated genes USH1G, USH1C, CDH23, and CIB2, suggesting that Müller glial cells may be more mechanistically relevant to Usher syndrome pathology than previously considered." (PMID 38474133, 2024). "We investigated other clinical features of Usher syndrome, by extending our analyses beyond the inner ear and assessing the retinal function of CIB2−/− mice on electroretinograms (ERGs)." (PMID 29084757, 2017). "Here the authors show that protein responsible for Usher syndrome, CIB2, interacts with these channels and is essential for their function and hearing in mice." (PMID 28663585, 2017). "A meta-analysis found that mutations in CIB2 were never detected in the declared cases of Usher syndrome." (PMID 40076845, 2025). "While affected by profound hearing loss, patients showed no vestibular or retinal impairment, thus confirming that the absence of CIB2 was not a direct cause of Usher syndrome." (PMID 35408910, 2022). "Potential causative variants were identified in genes associated with nonsyndromic hearing loss (CIB2, COL11A1, ILDR1, MYO15A, TMPRSS3, and WFS1), nonsyndromic hearing loss or Usher syndrome (CDH23, MYO7A, PCDH15, and USH2A), and other syndromic forms of hearing loss (CHD7, OPA1, and SPTLC1)." (PMID 34837038, 2022). "Mutations in CIB2 (OMIM #605564), previously identified as causing USH1J, have subsequently been suspected to cause autosomal recessive non-syndromic hearing loss and not Usher syndrome." (PMID 33121974, 2020). "Usher syndrome is heterogenous, both in terms of clinical presentation and genetic origin, with a number of diverse genes known to carry pathogenic mutations (Type 1: MYO7A, USH1C, PCDH15, CDH23, USH1G, and CIB2; Type 2: USH2A, ADGRV1, and WHRN; Type 3: CLRN1)." (PMID 38474133, 2024). "PDZD7 may act as a modifier gene for USH, but HARS, ABHD12, CIB2, CEP250, CEP78, ESPN, and ARSG could be grouped in a separate syndromic “deaf–blindness” category, to avoid diagnostic pitfalls and misinformation during genetic counseling for Usher syndrome." (PMID 35353227, 2022). "These mutations may not lead to Usher syndrome, but the possibility of some types of CIB2 mutations conferring predisposition to age-related macular degeneration should be considered." (PMID 35353227, 2022). "This essential role of CIB2 in mechanotransduction and cell survival that, we show, is restricted to the cochlea, probably accounts for the presence in CIB2−/− mice and CIB2 patients, unlike in Usher syndrome, of isolated hearing loss without balance and vision deficits." (PMID 29084757, 2017). "Altogether, our findings demonstrate that CIB2 variants may not lead to Usher syndrome, suggesting that caution should be taken when providing genetic counselling for patients with CIB2 mutations." (PMID 29084757, 2017).
Usher syndrome (continued). "Currently, up to 13 genes have been associated with Usher syndrome: MYO7A, USH1C, CDH23, PCDH15, USH1G, and CIB2 are responsible for USH1, although the role of CIB2 in the Usher syndrome has recently been put on doubt." (PMID 31231422, 2019). "Therefore, caution is required when providing genetic counselling for families with patients carrying CIB2 mutations, as these mutations may not necessarily lead to Usher syndrome." (PMID 29084757, 2017). "The CIB2 protein binds to myosin VIIa and whirlin, which makes it a part of the usher syndrome interactome, but none of the protein is required for proper localization of Cib2 in the mouse stereocilia." (PMID 27771768, 2017). "However, as shown here in both mice and humans, CIB2 function seems to be dispensable for balance and vision, and therefore, caution is required when providing genetic counselling for families with patients carrying CIB2 mutations, as these mutations may not necessarily lead to Usher syndrome." (PMID 29084757, 2017). "These expression studies therefore provided no support for a potential link between CIB2 and Usher syndrome." (PMID 29084757, 2017).
hearing loss (15 papers, 2015 to 2025). "Given the functional correlation between TMC proteins and CIBs in inner ear hair cells, targeted Cib2 gene therapy warrants systematic investigation, with Tmc1’s therapeutic success supporting its potential for treating CIB2-related hearing loss." (PMID 40076845, 2025). "Multiple missense mutations of human CIB2 or TMC-1 are associated with non-syndromic hearing loss by either impeding the interaction between TMC-1 and CIB2 or by reducing the Ca2+ binding propensity of CIB214." (PMID 36224384, 2022). "At present, 13 identified mutations in the gene encoding CIB2 have been associated with different forms of hearing impairment, including five nonsense mutations with an ultra-rare frameshift and eight missense mutations." (PMID 35408910, 2022). "So far, six missense mutations of CIB2 have been reported as responsible for hearing loss in humans." (PMID 28663585, 2017). "CIB2 is an important deafness gene whose mutations are associated with nonsyndromic deafness DFNB48 and syndromic deafness USH1J, but its biological function and the mechanism through which CIB2 mutations cause hearing loss remain elusive." (PMID 29255404, 2017). "Here we report a novel (c.556C>T; p.(Arg186Trp)) transition mutation in the CIB2 gene identified through whole exome sequencing (WES) in a Caribbean Hispanic family with non-syndromic hearing loss." (PMID 26426422, 2015). "The interaction with TMC1 may be disrupted by the N-terminal truncation of CIB2 or several other missense mutations (p.E64D, p.F91S, and p.C99W) associated with hearing loss, which located in the central region of CIB2." (PMID 40076845, 2025). "In humans, the mutations of CIB2 are associated with hearing loss." (PMID 40076845, 2025). "It should be reported that a recent study disqualified CIB2 as a USH1J-related gene, however the E64D variant was found to be associated with autosomal recessive non-syndromic hearing loss." (PMID 30174586, 2018). "The genes Cib2 and Espn are involved in the formation of stereocilia in the inner ear, and their disruption can lead to hearing impairment." (PMID 28491023, 2017). "Notably, CIB2 mutations have been genetically linked to human hereditary hearing impairment, yet the AAV-based restoration of Cib2 or its paralog Cib3 in Cib2-mutant mice remains unexplored." (PMID 40076845, 2025). "For example, the CIB2-R186W mutation disrupts the hydrophobic core (corresponding to Phe-173 in CIB1), which affects ligand binding or structural stability, ultimately leading to genetic deafness, such as in hearing loss." (PMID 40076845, 2025). "We also sought patients with CIB2 mutations, leading to the identification of two new nonsense mutations predicted to produce CIB2‐truncated proteins in patients with nonsyndromic hearing loss without signs of retinitis pigmentosa or vestibular dysfunction." (PMID 29084757, 2017). "Our biochemical and biophysical study highlights a number of clear structural and functional differences with CIB1, which may thus pose the molecular basis for understanding the malfunctioning of CIB2 in USH1J and possibly other genetic diseases causing hearing loss." (PMID 30174586, 2018). "Notably, IHCs remain intact for a few postnatal weeks in Cib2 mutants, which might provide a therapeutic window for the treatment of Cib2-related hearing impairments." (PMID 28663585, 2017).
deafness (13 papers, 2014 to 2025). An inherited or acquired condition characterized by the complete loss of the ability to hear from one or both ears. "Those deafness-associated genes included well-known HC genes, such as Cdh23 (Cadherin-23) and Cib2 (calcium and integrin binding family member 2), which were also detected in one previous single-cell SGN RNA-Seq study." (PMID 31913118, 2020). "However, a recent study found a distinct visual phenotype alongside deafness in a cib2-deficient mouse model, confirming the association of CIB2 defects with syndromic inherited retinal dystrophies (IRD) such as USH." (PMID 37427378, 2023). "Mutations in the gene encoding CIB2 have been associated with non-syndromic deafness." (PMID 35408910, 2022). "Furthermore, we report that calcium and integrin-binding protein 2 binds to the components of the hair cell mechanotransduction complex, TMC1 and TMC2, and these interactions are disrupted by deafness-causing Cib2 mutations." (PMID 28663585, 2017). "Perhaps other deafness-related mutations (e.g. p.R186W) in Cib2 might be less deleterious to hair cell mechanotransduction and might clarify the role of CIB2 in the adaptation of MET current when corresponding Cib2 mouse knockin models become available." (PMID 28663585, 2017). "Furthermore, not only N-terminal truncations of CIB2, but also several other deafness-associated missense mutations (p.E64D, p.F91S, and p.C99W), located in the central region of CIB2, also disrupt its interaction with TMC1." (PMID 28663585, 2017). "Mechanotransduction currents are abolished in mice with null mutations in CIB2 and CIB3, resulting in deafness." (PMID 38354260, 2024). "Taken together, all these lines of evidence further support the plasticity of CIB2 in terms of structure and function as well as its fundamental role played in hearing and, thus, in deafness." (PMID 35408910, 2022). "Our findings show that MET responses, structural integrity of the hair bundles and hair‐cell survival in the mature cochlea are critically dependent on CIB2, the protein defective in DFNB48 isolated deafness and in USH1J." (PMID 29084757, 2017). "This explains why patients with CIB2 mutations mainly exhibit deafness rather than vestibular disorders, providing new insights into the study of functional compensation mechanisms." (PMID 41049429, 2025). "In human genetic studies, it has been clearly established that mutations in CIB2 cause only DFNB48-type deafness and do not affect visual function." (PMID 41049429, 2025). "Three out of six mutants (p.E64D, p.F91S, and p.C99W) affected interactions of CIB2 with TMC1 (bottom), suggesting that these mutations disrupt the putative TMC1-CIB2 complex in hair cells and thus cause deafness in humans." (PMID 28663585, 2017). "Consistently, loss‐of‐function mutations of CIB2 in humans also lead to profound deafness without vestibular or retinal dysfunction." (PMID 29084757, 2017). "Defects of CIB2, calcium‐ and integrin‐binding protein 2, have been reported to cause isolated deafness, DFNB48 and Usher syndrome type‐IJ, characterized by congenital profound deafness, balance defects and blindness." (PMID 29084757, 2017). "In recent years, several pathogenic variants of CIB2 were identified after the discovery of USH1J, in families with the DFNB48 form of isolated deafness but no signs of retinitis pigmentosa or vestibular dysfunction." (PMID 35353227, 2022). "To determine if the deafness causing mutation affects the ability to localize to the tips of filopodia, we over-expressed DsRed tagged CIB2WT and CIB2R186W constructs of human CIB2 along with non-tagged human Whirlin and GFP-Myosin 15a in COS-7 cells." (PMID 26426422, 2015). "In addition, mutations in MYO7A, USH1C, DFNB31, CIB2, CDH23 and PCDH15 were also reported in non-syndromic deafness without retinal degeneration and mutations in USH2A and CLRN1 have been reported in patients with isolated RP or retinal dystrophies and no deafness." (PMID 25211151, 2014).
ovarian carcinoma (7 papers, 2017 to 2025). A malignant neoplasm originating from the surface ovarian epithelium. "CIB2, significantly down-regulated in ovarian cancer, and low CIB2 expression was associated with poor prognosis in ovarian cancer patients." (PMID 35057823, 2022). "For instance, CIB2 is downregulated in ovarian cancer and associated with poor prognosis in ovarian cancer patients." (PMID 34162842, 2021). "Conversely, CIB2 has been shown to attenuate oncogenic signaling in ovarian cancer, and low CIB2 expression is associated with poorer survival of ovarian cancer patients." (PMID 33227088, 2020). "In ovarian cancer, CIB2 has been shown to operate as a possible tumor suppressor by decreasing tumor development and cell migration/invasion, therefore reduced CIB2 levels have been linked to a poor prognosis in patients." (PMID 39264588, 2024). "Our previous work demonstrated that mislocalised SPHK1, caused by loss of a negative regulator protein, calcium and integrin binding protein 2 (CIB2), promoted tumour growth, metastasis and chemotherapeutic resistance in ovarian cancer cell lines and a xenograft mouse model." (PMID 40356021, 2025). "Also, a recent study showed that similar to CIB1, CIB2 negatively regulates oncogenic signalling in ovarian cancer via its interaction with sphingosine kinase 1 (SK1), a regulator of the cellular balance between pro‐apoptotic and pro‐survival sphingolipids." (PMID 29084757, 2017).
nonsyndromic deafness (3 papers, 2017 to 2020). An auditory system disease that is associated with permanent hearing loss caused by damage to structures in the inner ear and/or the middle ear, which is not associated with other signs and symptoms. "Among the family members, the Cib1 and Cib2 genes are expressed in mouse cochlear hair cells, and mutations in the human CIB2 gene have been associated with nonsyndromic deafness DFNB48 and syndromic deafness USH1J." (PMID 29255404, 2017).
age-related macular degeneration (2 papers, 2022). Age-related loss of vision in the central portion of the retina (macula), secondary to retinal degeneration. "Age-related macular degeneration (AMD) is characterized by a deficit in autophagy associated with deficiency of calcium and integrin binding protein 2 (CIB2), which are essential for visual functions." (PMID 35163359, 2022).
atrial fibrillation (2 papers, 2016 to 2025). A disorder characterized by an electrocardiographic finding of a supraventricular arrhythmia characterized by the replacement of consistent P waves by rapid oscillations or fibrillatory waves that vary in size, shape and timing and are accompanied by an irregular ventricular response. "CIB2 expression is significantly reduced in atrial tissue from both atrial fibrillation patients and animal models." (PMID 40076845, 2025). "Moreover, numerous studies have implicated the paralogue CIB1 (38% identical and 59% similar to CIB2), in cardiac hypertrophy and atrial fibrillation, and in valvular heart disease." (PMID 26378684, 2016).
autism (2 papers, 2012 to 2021). Persistent deficits in social interaction and communication and interaction as well as a markedly restricted repertoire of activity and interest as well as repetitive patterns of behavior. "Interestingly, for each of the genes CIB2, FBRSL1, PACS2, KDM4B, and MYT1L, we found 2 individuals with autism with de novo variants in DAEs interacting with these genes." (PMID 34663447, 2021).